LXN (latexin)
Diseases named in the same sentence as LXN in open-access papers (continued):
Sharing a sentence is not in itself a finding about the gene and the disease.
tumor (continued). "For instance, sc-seq has uncovered malignant cell subclusters enriched in genes associated with histone deacetylase (HDAC) inhibitor response (ATF3, CAV1), inflammation (LXN, PGM1), and hypoxia-linked tumor metastasis (WSB1), highlighting their importance in tumor progression." (PMID 41450739, 2025). "LXN deficiency enhances PD-L2 expression rather than PD-L1 in macrophages, which lead to inhibition of T cells in tumor microenvironment." (PMID 36323670, 2022). "LXN expression reportedly affects the growth of several different tumours." (PMID 30914656, 2019). "A single publication to date demonstrates that LXN might be a retinoic acid responsive gene and impart tumour suppressive effects on CaP cells." (PMID 30914656, 2019). "Investigating the effects of LXN on immune cell function in the tumour microenvironment (TME) may reveal how observed intratumoural loss of LXN affects the prognosis of many adenocarcinomas." (PMID 30914656, 2019). "Canonically, LXN is thought to exhibit tumor suppressor-like functions." (PMID 26252227, 2015). "Its dysregulated expression in other tumors led us to hypothesize that latexin may have tumor suppressor properties in hematological malignancies." (PMID 23028717, 2012). "The molecular mechanism underlying latexin-mediated tumor inhibition was not through its canonical carboxypeptidase inhibitor activity." (PMID 23028717, 2012). "The downregulation of latexin expression in multiple tumor cell lines and tumor tissues suggests that latexin may be functionally involved in the suppression of cancer cell growth." (PMID 21466706, 2011). "Taken together, our results strongly suggest that latexin is a potential tumor suppressor." (PMID 21466706, 2011). "Thus, alterations of expression of these genes influenced by latexin expression strongly support the concept that latexin exerts a growth inhibitory function in tumor cells." (PMID 21466706, 2011). "In malignant tissues, the expression of LXN is generally reduced compared to normal tissues, and based on molecular evidence that LXN possesses an inhibitory effect on cancer cell growth and tumorigenicity, a possible tumor suppressor function has been proposed." (PMID 39202445, 2024). "Furthermore, LXN can play a tumour suppressive role in several different adenocarcinomas." (PMID 30914656, 2019). "To investigate the underlying molecular mechanism for the role of latexin expression in negative control of tumor cell growth, we examined the changes in the gene expression profile in response to latexin expression in C39-8 cells compared with MGC803 cells transfected with empty vector." (PMID 21466706, 2011). "Latexin (LXN) plays an important role in tumorigenesis and inflammatory response and as a tumor suppressor in many tumors." (PMID 36323670, 2022). "LXN has been reported to be a predominantly cytosolic protein in the leukeamic cell line FDC-P1, in murine HSCs and also in primary human breast adenocarcinoma." (PMID 30914656, 2019). "Overexpression of LXN gene in MGC803 cells inhibited colony formation and tumor growth in nude mice." (PMID 21466706, 2011). "In particular, GGACT, LXN, THY1, SYNPO2, ACMSD and COLEC11 showed no survival or recurrence associations from the tumor data, suggesting these as unique biomarkers from NAT." (PMID 37575948, 2023). "Latexin is a tumour-suppressor and negative stem cell regulator which induces removal of old stem cells and prevents their eventual transformation into tumour cells." (PMID 33807045, 2021). "Despite association with numerous processes including haematopoietic stem cell (HSC) fate, inflammation and tumour suppression, a clearly defined biological role for LXN is still lacking." (PMID 30914656, 2019). "Additionally, several tumor related genes, including Maspin, WFDC1, SLPI, S100P, and PDGFRB, were shown to be differentially expressed in MGC803 cells in response to latexin expression." (PMID 21466706, 2011).
tumor (continued). "Using our dataset and another high-quality dataset, we identified proteins that showed clinical prognosis and recurrence associations, of which GGACT, LXN, THY1, SYNPO2, ACMSD and COLEC11 were unique biomarkers identified from NAT that could not be revealed using tumor-based analysis." (PMID 37575948, 2023). "Through a literature survey, we identified that GPX3, LDOC1, LXN, and UCHL1, but not LIPG, have been reported as tumor suppressor genes, and that their expression was mediated by promoter DNA methylation." (PMID 26317789, 2015).
cancer (14 papers, 2011 to 2025). A tumor composed of atypical neoplastic, often pleomorphic cells that invade other tissues. "LXN deficiency in hematopoietic lineage exacerbates colorectal carcinogenesis, and targeted inhibition of PD-L2 ameliorates cancer growth in LXN-deficient mice." (PMID 36323670, 2022). "We observed the increased PD-L2 levels in LXN-deficient macrophage, we accordingly evaluated the effects of PD-L2 and PD-L1 blockade on cancer growth." (PMID 36323670, 2022). "Loss of latexin (LXN) expression negatively correlates with the prognosis of several human cancers." (PMID 30914656, 2019). "Although the carboxypeptidase inhibitor LXN has been widely studied in cancer, there is still little knowledge about its expression and possible role in non-cancerous tissues." (PMID 39202445, 2024). "This assumption is also supported by previous studies on LXN low-expressing cancer cell lines, where exogenous expression of LXN resulted in inhibition of cell growth." (PMID 39202445, 2024). "Loss of LXN in macrophage activates JAK1/STAT3/PD-L2 pathway, which contribute to the immune escape of cancer cells by attenuating the function of T cells in TME." (PMID 36323670, 2022). "Latexin is a tumor suppressor that reduces the transformation of senescent stem cells into cancer stem cells, showing a cancer-suppressive ability." (PMID 36212439, 2022). "In the two gene clusters, some genes associated with tumorigenesis and cancer progression, such as AGR2, MMP7, LXN, PIGR, and CRABP2, were identified." (PMID 36712886, 2022). "To assess the validity of these findings we utilised the Cancer genome atlas (TCGA) database to assess concurrence of LXN alterations in human cancer gene databases with the most differentially expressed genes in our transcriptome arrays." (PMID 30914656, 2019). "Our data demonstrate that LXN is highly expressed in normal prostate luminal cells but downregulated in high Gleason grade cancers." (PMID 30914656, 2019). "In contrast, secretory leukocyte protease inhibitor (SLPI) which is also a protease inhibitor but functions to enhance cancer invasion was downregulated by latexin expression to less than one half of control level." (PMID 21466706, 2011). "The expression of latexin was found predominantly in the cytoplasm of the three immortalized cell lines and in only three of ten cancer cell lines." (PMID 21466706, 2011). "Both C39-8 and C46 cells exhibited suppressed tumorigenicity and proliferation as compared to control MGC803 cells, suggesting exogenous expression of latexin in MGC803 cells inhibited cancer cell growth." (PMID 21466706, 2011). "Furthermore, in different cancer models the biological effects of LXN appear to be diverse and its biological function is increasingly multi-faceted." (PMID 30914656, 2019). "Methylation of Latexin will silence the Latexin gene and therefore permitting cancer metastasis." (PMID 26861290, 2016). "Western blot analysis of cytoplasmic and nuclear proteins revealed that latexin was located predominantly in the cytoplasm of human cells, and was detected in all three kinds of human immortalized cells and in three of ten human cancer cells tested in this work." (PMID 21466706, 2011). "An integrative analysis identified that enrichment of F. nucleatum was associated with host gene promoter methylation, including hypermethylation of tumor suppressor genes LXN and SMARCA2, for which gene expressions were downregulated in the HNSCC cohort from The Cancer Genome Atlas." (PMID 33218162, 2020). "Compared to cells transduced with lentiviral control particles (Mock), overexpression of LXN did not affect the viability of any of the cell lines tested, including the luminal-like cancer cell line, LNCaP." (PMID 30914656, 2019). "When we compared the expression levels of LXN between non-malignant and malignant prostate tissue, we found that LXN was significantly repressed in high Gleason grade cancers." (PMID 30914656, 2019).
cancer (continued). "Whilst overexpression of LXN in prostate epithelial basal cells did not affect cell fate, LXN overexpression in the luminal cancer line LNCaP reduced plating efficiency." (PMID 30914656, 2019). "To determine the biological effects of LXN in prostate epithelial cells, we generated lentiviral vectors to induce robust and stable overexpression of LXN in normal (PNT1A), Benign (BPH-1) and cancer cell lines P4E6 (basal-like) and LNCaP (luminal –like)." (PMID 30914656, 2019). "The mechanism by which the LXN gene expression is suppressed in cancer cells has not been demonstrated." (PMID 21466706, 2011). "Moreover, differential expression of genes induced by ectopic latexin expression in cancer cells were screened by microarray analysis, and correlation of LXN promoter methylation with latexin expression was analyzed in human cells." (PMID 21466706, 2011). "Our finding that LXN overexpression potentially increases immune signaling, possibly through IFN-γ and its related genes is further supported by several studies that highlight the synergy between interferons and atRA in clearing infection, and increasing apoptosis in cancer cells." (PMID 30914656, 2019).
adenocarcinoma (1 paper, 2019). A common cancer characterized by the presence of malignant glandular cells. "Despite multiple attempts to determine a role for loss of LXN expression in adenocarcinoma, thorough characterisation of LXN in normal epithelia or malignancy is still lacking." (PMID 30914656, 2019).
colorectal (1 paper, 2022). "Bone marrow transplantation prove that LXN-deficient hematopoietic lineage accelerates AOM/DSS-induced colorectal tumorigenesis." (PMID 36323670, 2022).
LXN also shares sentences with these, for which no sentence is quoted: cardiovascular disease (2 papers); acute myelogenous leukemia (1); Hematochezia (1); hepatocellular carcinoma (1); leukemia (1); liver cancer (1); liver cirrhosis (1); lung carcinoma (1); metabolic disorders (1); metabolic syndrome (1); nephrolithiasis (1); sarcopenia (1); thyroid carcinoma (1).